CDC25B (cell division cycle 25B)
Description:
Tyrosine protein phosphatase which functions as a dosage-dependent inducer of mitotic progression. Directly dephosphorylates CDK1 and stimulates its kinase activity. Required for G2/M phases of the cell cycle progression and abscission during cytokinesis in a ECT2-dependent manner. The three isoforms seem to have a different level of activity.
Synonyms: MPIP2
Tractability: Small molecule: a structure with a bound ligand is known; a high-quality ligand is known; it has a binding pocket of medium quality; it belongs to a druggable protein family. PROTAC: ubiquitination databases record sites on it; a small molecule that binds it is known.
Target class: Phosphatase; Serine/threonine/tyrosine protein phosphatase; Enzyme; Protein Phosphatase
Chemical probes: ADOCIAQUINONE B
Gene: Protein-coding gene on chromosome 20 (3,786,772 to 3,806,730, forward strand). Ensembl gene ENSG00000101224.
Subcellular location: Cytoplasm, cytoskeleton, microtubule organizing center, centrosome; Cytoplasm, cytoskeleton, spindle pole
Subcellular location (Human Protein Atlas): Vesicles; Mitotic spindle
Pathways (Reactome):
Cell Cycle: Cyclin A/B1/B2 associated events during G2/M transition; Cyclin A:Cdk2-associated events at S phase entry
Developmental Biology: Regulation of MITF-M-dependent genes involved in cell cycle and proliferation
Disease: Deregulated CDK5 triggers multiple neurodegenerative pathways in Alzheimer's disease models
Gene Ontology:
Molecular function: phosphoprotein phosphatase activity; protein binding; protein kinase binding; protein tyrosine phosphatase activity
Biological process: positive regulation of cytokinesis; positive regulation of G2/M transition of mitotic cell cycle; positive regulation of mitotic cell cycle; protein phosphorylation; G2/M transition of mitotic cell cycle; mitotic cell cycle; positive regulation of cell population proliferation; positive regulation of G2/MI transition of meiotic cell cycle; positive regulation of cell cycle G2/M phase transition
Cellular component: centrosome; spindle pole; cytoplasm; cytosol; nucleoplasm; nucleus
Genetic constraint (gnomAD): Loss-of-function variants: 31 observed, 65.25 expected, observed/expected ratio (o/e) 0.48, 90% interval 0.36 to 0.64. The upper end of that interval is the gene's LOEUF score, 0.64, which puts it in group 2 of 6, group 1 being the genes least tolerant of losing a copy. Missense variants: 722 observed, 779.71 expected, observed/expected ratio (o/e) 0.93, 90% interval 0.87 to 0.99. Synonymous variants: 340 observed, 302.29 expected, observed/expected ratio (o/e) 1.12, 90% interval 1.03 to 1.23.
Homologues: Orthologues: chimpanzee CDC25B (99% identical), macaque CDC25B (93% identical), pig CDC25B (88% identical), guinea pig CDC25B (83% identical), rat Cdc25b (82% identical), mouse Cdc25b (81% identical), dog CDC25B (81% identical), tropical clawed frog cdc25b (48% identical), Caenorhabditis elegans cdc-25.2 (20% identical), Caenorhabditis elegans cdc-25.3 (16% identical). Paralogues in human: CDC25A (44% identical), CDC25C (30% identical).
Diseases named in the same sentence as CDC25B in open-access papers:
CDC25B is named in the same sentence as 96 diseases in open-access papers, as found by Europe PMC text mining. Sharing a sentence is not in itself a finding about the gene and the disease. The quoted sentences say what the papers report.
breast carcinoma (17 papers, 2010 to 2025). "The ability of rosmarinic acid to inhibit MMP-1, MMP-2, MMP-9, aldose reductase, and CDC25B activity may underlie how rosmarinic acid is able to inhibit the development of breast cancer." (PMID 40176865, 2025). "Recent research has showcased an overexpression of the CDC25B gene in a spectrum of human cancers, including breast cancer, nasopharyngeal carcinoma, and hepatocellular carcinoma." (PMID 38730293, 2024). "CDC25b, is a key cell cycle regulator and also an oncogene with an over-expression observed in breast cancer, lung cancer, and CRC." (PMID 34202689, 2021). "And moreover, in human breast cancer, miRNA-211 directly inhibit CDC25B expression in breast cancer cells, alters other related target proteins CCNB1 and FOXM1, and then inhibits breast cancer cells growth, migration, and invasion and lead G2/M arrest." (PMID 28924391, 2017). "Many reports showed that Cdc25A and Cdc25B were associated with breast cancers, colorectal cancers, non-small cell lung cancers and so on." (PMID 37468905, 2023). "Studies have showed that highly expression of CDC25B in many types of cancer like esophageal squamous carcinoma, colorectal cancer, non-small cell lung cancer, endometrial carcinoma, pancreatic ductal adenocarcinoma, and breast cancer." (PMID 35287752, 2022). "CDC25B has been found to be overexpressed in many primary tumors, including breast cancer." (PMID 33385163, 2020). "Furthermore, dual inhibition of CDC25B and PP2A further inhibits growth of 3D organoids isolated from patient derived xenograft model of breast cancer compared to CDC25B inhibition alone." (PMID 33385163, 2020). "Moreover, CDC25B is overexpressed in most tumor types, including head and neck, ovary, colon, and breast cancers, suggesting its potential as a target for novel anticancer drugs." (PMID 25384584, 2015). "In breast cancers, ZER caused G2/M phase cell cycle arrest associated with downregulation of cyclin B1, Ddk1, Cdc25C, and Cdc25B and Bax/Bak-mediated apoptosis in human breast cancer (MDA-MB-231 and MCF-7) cells and retarded growth of MDA-MB-231 xenografts in vivo." (PMID 25025076, 2014). "No endogenous associations of CDC25B with LKB1 or CaMKKβ were detected in breast cancer cells." (PMID 33385163, 2020). "Among those 11 protein candidates, we found 6 proteins that are involved in the progression and development of breast cancer, those are MMP-1, MMP-2, MMP-9, MMP-12, M-phase inducer phosphatase-2 (CDC25B), and Aldose reductase." (PMID 40176865, 2025). "CDC25B dephosphorylates and activates Cyclin-dependent Kinase 1/Cyclin B (CDK1/Cyclin B), which have been shown to be overexpressed in breast cancer and promote cell cycle progression." (PMID 40454580, 2025). "Also, a study on breast cancer cells (MDA-MB-231 and MCF-7) showed that Zerumbone could lead to G2/M phase cell cycle arrest associated with Bax/Bak-mediated apoptosis and downregulation of cyclin B1, Ddk1, Cdc25C, and Cdc25B." (PMID 32454937, 2020). "Breast cancer cells (BT549 and HS578T) showed reduced AMPK phosphorylation at threonine 172 upon CDC25B knockdown." (PMID 33385163, 2020). "Among them, 5 (TOP2A, HER3, CDC25B, MCM2 and TUBB) are from breast cancer cell lines and, in particular, HER2 positive cells (ZR7530 is [ER+PR−]HER2+, HCC2218 and BT474 are [ER−PR−]HER2+78)." (PMID 28754978, 2017). "Furthermore, cells with CDC25B transient knockdown showed slower cell growth compared with control siRNA transfected BT549 and HS578T breast cancer cells, a process that was through the blocking of cell cycle progression." (PMID 33385163, 2020).
breast carcinoma (continued). "CDC25B depletion leads to metformin resistance and PP2A inhibition overcomes the resistance to metformin in breast cancer patient derived organoid models, suggesting that CDC25B–PP2A–AMPK axis is an important regulator of breast cancer growth, AMPK activation and metformin response." (PMID 33385163, 2020). "In addition, we treated MDA-MB-436 breast cancer cells with M-FOXM1 Apt and measured the levels of FOXM1, Cdc25B, and Cyclin B1." (PMID 28358012, 2017). "Genes enriched in the top breast cancer cell lines are TOP2A, HER3, CDC25B, MCM2 and TUBB." (PMID 28754978, 2017). "Indeed, we demonstrated that CDC25B bound to PP2A specifically through its C subunit in both cytoplasm and nucleus, with the B56δ subunit in the complex, leading to a decreased PP2A phosphatase activity and increased breast cancer cell growth." (PMID 33385163, 2020). "CDC25B, however, had no impact on metformin response in ER positive or HER2 positive breast cancer cells." (PMID 33385163, 2020). "Our results show that FK-3000 decreased levels of phosphorylated CDC25B (phospho-CDC25B) but neither CDC25A nor CDC25C, and induced G2/M phase arrest in human breast carcinoma cell lines MDA-MB231 and MCF-7." (PMID 25384584, 2015).
ovarian carcinoma (13 papers, 2017 to 2025). A malignant neoplasm originating from the surface ovarian epithelium. "CDC25B is overexpressed in ovarian cancer and is associated with poor patient prognosis; the CDC25B inhibitor WG-391D can significantly inhibit the malignant proliferation of ovarian cancer cells and the growth of transplanted tumors." (PMID 35743699, 2022). "Furthermore, according to analysis using the Kaplan Meier-plotter online tool, CDC25B expression was positively associated with poor prognosis in ovarian cancer patients." (PMID 31024841, 2019). "For instance, the novel inhibitor WG-391D tested in ovarian cancer mouse models, presented advantageous effects to inhibiting tumor growth by down-regulating CDC25B." (PMID 38313315, 2024). "First, the suppressive effect on the phosphorylation of CDC25B in malignant ovarian cancer cells is strong, such that it is more difficult to detect G2/M phase cell cycle arrest in OVCAR3 than in 293T cells." (PMID 35017636, 2022). "We next measured known FOXM1 downstream targets CCNB1 and CDC25B expression by qPCR in ovarian cancer cells treated with compounds (40 μm; 48 h)." (PMID 35680842, 2022). "In ovarian cancer, CDC25B inhibitor, WG-391D blunted cell proliferation, migration, resulting in cell cycle arrest at the G2/M and apoptosis." (PMID 33442418, 2021). "Cell division cycle 25B (CDC25B) has been identified to be correlated with poor prognosis of ovarian cancer." (PMID 32742495, 2020). "The inhibition of CDC25B by WG-391D is irreversible, and WG-391D should therefore exhibit potent antitumor activity against ovarian cancer." (PMID 31024841, 2019). "This study is the first to demonstrate a rationale for treating ovarian cancer using CDC25B down-regulators." (PMID 31024841, 2019). "This study shows that CDC25B is strongly over-expressed in ovarian tumors compared with normal ovarian tissues and that CDC25B is universally strongly expressed in ovarian cancer and primary ovarian tumor cell lines." (PMID 31024841, 2019). "Overall, this study demonstrates that WG-391D can efficiently inhibit ovarian cancer tumorigenesis by down-regulating CDC25B." (PMID 31024841, 2019). "Analysis of mRNA array data, using the Kaplan Meier-plotter online database, showed that CDC25B overexpression was positively associated with poor PFS and PPS of ovarian cancer patients." (PMID 31024841, 2019). "This study indicates that CDC25B down-regulators may be valuable for the clinical treatment of ovarian cancers." (PMID 31024841, 2019). "Novel CDC25B inhibitors with high efficiency could be very valuable for the clinical treatment of ovarian cancer." (PMID 31024841, 2019). "In conclusion, this study demonstrated that CDC25B was over-expressed in ovarian cancers." (PMID 31024841, 2019). "In conclusion, this study demonstrates that WG-391D exhibits strong antitumor activity against ovarian cancer and indicates that the down-regulation of CDC25B by inhibitors could provide a rationale for ovarian cancer therapy." (PMID 31024841, 2019). "In addition, FDI-6, a recent developed small molecule inhibitor of FOXM1 which transcriptionally upregulates CDC25B expression, suppressed CDC25B expression in breast and ovarian cancer cells." (PMID 30791455, 2019). "Hence, CDC25B is a potentially valuable target in the development of chemotherapeutics for the treatment of ovarian cancer." (PMID 31024841, 2019). "We hypothesized that CDC25B down-regulators could be valuable for targeted therapies against ovarian cancer." (PMID 31024841, 2019). "With the use of ovarian cancer PDXs, CDC25B inhibitor WG-391D 95, and BAY-876 96 have been proved to regress ovarian cancer growth in PDXs." (PMID 32742495, 2020).
ovarian carcinoma (continued). "CDC25B is involved in cell cycle regulation and DNA damage response and has been targeted by thiostrepton, FDI-6, and siomycin A in preclinical studies for the treatment of platinum-resistant ovarian cancer." (PMID 41375077, 2025). "In the case of ovarian cancer studies, found that the overexpression investigated using immunohistochemistry that the poor prognosis had a link to the overexpression of CDC25A and CDC25B in a sample of 106 patients." (PMID 38313315, 2024). "There have been studies related to CDC25B-selective inhibitors for the treatment of other tumors, such as gastric cancer, ovarian cancer, and nonmelanoma skin cancer." (PMID 39371450, 2024). "Also, high CDC25B expression levels were universally detected in both primary ovarian cancer cell lines (GFY004, GFY005, CZ001, and CZ006) and representative ovarian cancer cell lines (SKOV3 and HO8910PM)." (PMID 31024841, 2019). "All of these compounds were screened out using in vitro chemical assays because they reversibly inhibit the catalytic dephosphorylation activity of CDC25B, but none have entered clinical trials for ovarian cancer therapy." (PMID 31024841, 2019). "In this study, a novel small molecule compound, WG-391D, synthesized in our laboratory, was found to efficiently inhibit the expression, but not the catalytic dephosphorylation activity, of CDC25B in ovarian cancer cells." (PMID 31024841, 2019). "Phosphorylated epitope from cell division cycle 25B (CDC25B) was overexpressed in pancreatic cancer (targeting ENO1), while citrullinated epitopes from ENO1 and metallopeptidase 21 (MMP21) were specifically upregulated in ovarian cancer and melanoma, respectively." (PMID 40629481, 2025). "All previously reported CDC25B inhibitors have been identified by their ability to reversibly inhibit the catalytic dephosphorylation activity of CDC25B in vitro; however, none of these compounds have entered clinical trials for ovarian cancer therapy." (PMID 31024841, 2019).
colorectal cancer (11 papers, 2011 to 2023). A primary or metastatic malignant neoplasm that affects the colon or rectum. "Here we describe the antigenicity of these colorectal cancer associated proteins, identify T-cell epitopes suitable for inclusion in a vaccine, and demonstrate how a vaccine with two of the antigens, CDC25B and COX2, consistently reduced tumor development in two mouse models." (PMID 34526999, 2021). "Significantly higher levels of CDC25B-specific IgG antibodies were observed in patients with colorectal cancer (median, 0.28 μg/ml; range, 0.01-3.34 μg/ml) as compared to volunteer donors (median, 0.20 μg/ml; range, 0.1-0.61 μg/ml; p=0.041)." (PMID 34526999, 2021). "CDC25B is overexpressed in over 40% of colorectal cancers and in multivariate analysis is an independent predictor of poor prognosis (risk ratio for death 3.7 as compared to non-expressers)." (PMID 34526999, 2021). "MiR-141 was also reported to target SIP1 in colorectal cancer and CDC25B in renal cell carcinoma." (PMID 24551096, 2014). "Here, BTG1 overexpression inhibited proliferation, induced differentiation, autophagy, and apoptosis in colorectal cancer cells (p2 arrest might be related to Cyclin B1 and Cdc25B hypoexpression in HCT-15 transfectants, while G1 arrest in HCT-116 transfectants overexpressing p21 and p27." (PMID 27447746, 2017). "We evaluated 13 putative class II epitopes derived from CDC25B, COX2, FASCIN1, and RCAS1 and corresponding recombinant protein for IFN-γ secretion using PBMC derived from colorectal cancer patients and volunteer donors." (PMID 34526999, 2021). "Serum IgG for CDC25B, COX2, RCAS1, and FASCIN1 was significantly elevated in colorectal cancer patient sera compared to volunteers (CDC25B p=0.002, COX-2 p=0.001, FASCIN1 and RCAS1 p<0.0001)." (PMID 34526999, 2021). "Abnormal expression of Cdc25B has been reported in a number of carcinomas, such as non-small cell lung cancer, colorectal carcinomas, ovarian, esophageal, prostate, gastric and pancreatic cancers." (PMID 22132193, 2011).
gastric cancer (10 papers, 2002 to 2025). A primary or metastatic malignant neoplasm involving the stomach. "Consistently, the over-expression of CDC25B in gastric cancer was reported to be associated with advanced stage and deep invasion, and also with high rates of lymphatic invasion and lymph node metastasis." (PMID 18269767, 2008). "In gastric carcinoma, cdc25B expression was associated with advanced stage and deep invasion." (PMID 12085185, 2002). "PAH and gastric cancer have two (CDC25B, and IFI6) common overregulated genes located in the nucleoplasm, along with fifteen TFs, the transmembrane helix, and the endoplasmic reticulum membrane, related to negative regulation of the apoptotic process." (PMID 39791702, 2024). "Additionally, prior research has shown that c-MYC induces the invasion and migration of gastric cancer cells by upregulating CDC25B and downregulating YWHAE expression." (PMID 41184982, 2025). "Poor prognosis has been reported in gastric cancer patients with high CDC25B expression." (PMID 39371450, 2024). "CDC25A and CDC25B, being oncogenes, are over-expressed in many different primary human cancers, such as head and neck cancer, poorly differentiated non-small cell lung cancer, advanced stage gastric cancer, non-Hodgkin's lymphomas, colon cancer, esophagus cancer, breast cancer, and ovarian cancer." (PMID 18269767, 2008). "In gastric cancer cell lines, YWHAE was able to inhibit the cell proliferation, invasion and migration through the reduction of MYC and CDC25B expression." (PMID 27863420, 2016). "In addition, YWHAE silencing induces cell proliferation, invasion and migration through the upregulation of CDC25B and MYC in gastric cancer cells." (PMID 35515139, 2022). "Furthermore, it has been reported not long ago that YWHAE silencing induced cell proliferation, invasion, and migration through the upregulation of CDC25B and MYC in gastric cancer cells in accordance with our conclusion above." (PMID 35515139, 2022). "Another study demonstrated that 14–3-3ε inhibited gastric cancer (GC) cell proliferation by reducing MYC and CDC25B expression." (PMID 38279176, 2024). "In gastric cancer cell lines, YWHAE expression is significantly upregulated, and can inhibit cell proliferation, invasion, and migration by reducing the expression of MYC and CDC25B; whereas MYC induces cell proliferation, invasion, and migration by enhancing CDC25B, and reducing YWHAE expression." (PMID 34107979, 2021). "For this, we analyzed the YWHAE, CDC25B, and MYC expression in YWHA-silenced, CDC25B-silenced, and MYC-silenced gastric cancer cell lines, as well as in gastric cancer and non-neoplastic gastric samples." (PMID 27863420, 2016).